MALAT1 (metastasis associated lung adenocarcinoma transcript 1)
Diseases named in the same sentence as MALAT1 in open-access papers (continued):
Sharing a sentence is not in itself a finding about the gene and the disease.
cancer (continued). "MALAT1 was observed to be highly expressed in cancer tissues and it was initially observed in the metastatic non-small lung cancer tissues." (PMID 36387279, 2022). "MALAT1 has been found to promote cell proliferation and migration of cancer cells by regulating the expression of genes promoting metastases, e.g., RASSF6, HNF4G, CA2, ROBO1, MIA2." (PMID 35887000, 2022). "The miR-20b-5p/Oct4 axis is regulated by MALAT1 that mediates stem cell-like properties in human cancer." (PMID 36289596, 2022). "Numerous studies have indicated that MALAT1 has a significant effect on cancer development and progression." (PMID 35320950, 2022). "Despite the role of MALAT1 as a cancer biomarker, it can be considered a therapeutic target in cancer patients as well." (PMID 36163080, 2022). "For instance, MALAT1 is over-expressed in many cancer cells to control their proliferation, invasion, migration, and apoptosis." (PMID 35228564, 2022). "In terms of biomarkers for cancer diagnosis, studies have shown that the upregulation of MALAT-1 in peripheral blood can reflect the presence of NSCLC with a specificity of up to 96%." (PMID 36360316, 2022). "Recent studies have shown that the ceRNA network in TC plays a regulatory role and corresponding mechanisms in the development of cancer, such as lncRNA MALAT1 function as a ceRNA via sponging miR-200a-3p to derepress the FOXA1 expression." (PMID 35913967, 2022). "We investigated a possible role of lncRNA MALAT1 in CTCL cells because of its documented involvement in cancer metastasis." (PMID 36059695, 2022). "It has been reported that MALAT1 regulates cancer metabolism and the Warburg effect via the mTOR pathway in HCC, and also regulates MYBL2 expression level in HCC by affecting the alternative splicing of its pre-mRNA." (PMID 35557985, 2022). "LncRNA MALAT1 is a classical carcinogen in various tumors, controlling several aspects of cancer progression." (PMID 35557985, 2022). "Median relative expression of MALAT1 was significantly higher in cancer tissues than in PANTs (5.42 ± 3.84 vs. 0.048 ± 0.032, p < 0.001), confirming that MALAT1 was markedly upregulated in HCC." (PMID 36685103, 2022). "The lncRNA MALAT1, shows dysregulated expression across multiple cancers, including lung cancer and breast cancer." (PMID 35159022, 2022). "While MALAT1 is dysregulated in many types of human cancers and has been proposed as a “broad-spectrum” prognostic marker for poor clinical outcomes, its mechanisms of action in individual cases appear to be different and are dependent on cancer types." (PMID 36563164, 2022). "Previous studies have shown that MALAT1 can upregulate SRSF1-mediated series of cancer-promoting splicing events." (PMID 34750493, 2022). "These observed changes in the OVCAR-3 cancer cells after treatment with RA confirmed its anticancer activity induced by apoptosis, inhibition of cell migration, and modulation through lncRNA MALAT-1 expression." (PMID 36365218, 2022). "Metastasis-associated lung adenocarcinoma transcript 1 (MALAT1) is located on chromosome 11q13 and has been identified to be involved in cancer development and progression." (PMID 35327655, 2022). "The expression of MALAT1 has been upregulated in multiple cancer types include liver, cervix, breast, colorectal, renal, prostate, gastric and other cancers." (PMID 35305641, 2022). "Due to its ubiquitous and enriched expression, MALAT1 has been examined by many researchers in order to elucidate the pathogenesis of various diseases, including cancers, cardiovascular disease, and diabetes." (PMID 35954272, 2022). "On the other hand, lncRNA MALAT-1 was observed to be overexpressed in different cancer cell lines and to lower KEAP1 activity." (PMID 36077530, 2022). "Previously, some studies have confirmed the role of MALAT1 in the migration and invasive properties of various cancer cells." (PMID 35281907, 2022).
cancer (continued). "The lncRNA MALAT1 is similarly overexpressed in various cancer types, with increased MALAT1 levels being highly predictive of poor patient prognosis (Gutschner, Hammerle, & Diederichs, 2013)." (PMID 34668345, 2022). "An exosomal MALAT1 that can be delivered to cancer cells and sponges miRNAs has also been described." (PMID 35922756, 2022). "Since the MALAT1 can facilitate cancer advancement with the regulation of gene expression, the expression of apoptosis genes was assessed in DU-145 cells." (PMID 36163080, 2022). "Together, our results not only reinforce the notion of MALAT1 being functionally diverse in human cancers but also indicate that the functional module consisting of MALAT1, PTBP1, and PSF should be implicated in the pathogenesis of HCC." (PMID 36563164, 2022). "MALAT1 disorders are involved in regulating cell cycle, proliferation, and migration various cancers." (PMID 35368894, 2022). "The concatenated m6A residues on MALAT1 can allow YTHDC1 to obtain nuclear speckles for modifying the expression of key oncogenes to enhance the metastatic potential of cancer cells." (PMID 35534472, 2022). "Further, RT-PCR indicated a dose-dependent increase in the expression level of lncRNA MALAT-1 in OVCAR-3 cancer cells after treatment with RA." (PMID 36365218, 2022). "MALAT1 upregulation is known in different cancers, including prostate, colorectal, esophageal, endometrial, melanoma, hepatocellular, and ovarian cancers." (PMID 36163080, 2022). "The prognostic significance of MALAT1 has been revealed in cancers of the breast, lung, pancreas, and prostate." (PMID 35664303, 2022). "Compared with the expression in adjacent non-carcinoma tissues, MALAT1 expression is higher in EC tissues and correlates with unfavorable prognosis." (PMID 35645836, 2022). "Contrary to our results in the kidney, Malat1 and p21 were found to be inversely regulated in various carcinomas." (PMID 34697716, 2022). "MALAT1 is abnormally expressed in breast cancer, liver cancer, gastric cancer, pancreatic cancer, and other malignant tumors." (PMID 34761116, 2021). "For example, the lncRNAs, HOX transcript antisense RNA (HOTAIR), metastasis associated lung adenocarcinoma transcript 1 (MALAT-1) and H19 have all been reported as functional contributors of carcinogenesis or cancer growth." (PMID 34385891, 2021). "Expression, clinical significance, and function of lncRNA MALAT1 in pan-cancer exist as big difference." (PMID 34308750, 2021). "By competitively binding with miR-140, a variety of lncRNAs, such as lncRNA XIST, lncRNA MALAT1 and lncRNA H19, can promote cancer progression via facilitating the proliferation, migration and invasion of cancer cells in vitro and metastasis in vivo." (PMID 34496800, 2021). "In LUAD and BLCA, MALAT1 were both associated with CD8 + T cell, CD4 + T cell, DC cell, Tregs cell, Mast cell, cancer-associated fibroblast, common lymphoid progenitor, eosinophil, MDSC, and T-cell follicular helper cell infiltration." (PMID 34308750, 2021). "Although an established inverse significant correlation between MALAT1 and miRNA-101 was stated in different forms of cancer, the clinical relevance of this correlation in CRC remains to be scrutinized." (PMID 34200314, 2021). "A variety of studies have found the aberrant expression of MALAT1 in many cancer types, and the overexpression of which is shown to be associated with metastasis and poor survival." (PMID 34164906, 2021). "In NSCLC, MALAT1 promoted cancer cell migration in vitro and tumor formation and growth in vivo, and a high expression level of MALAT1 is associated with poor prognosis." (PMID 34745970, 2021). "One of the main mechanisms of MALAT1 in posttranslational regulation is its function as a ceRNA that leads to the progression of various cancers." (PMID 34771549, 2021). "Recent studies have suggested that the lncRNA MALAT1 is involved in the process of EMT in cancer cells through a variety of mechanisms." (PMID 34769245, 2021).
cancer (continued). "Both upregulation and downregulation of lncRNAs involved in many physiological processes, such as MALAT1, PLUT, and CARMN, are associated with the onset of various cancers, as well as metabolic, cardiovascular, and neurological disorders." (PMID 33925370, 2021). "DMS-Seq data from K562 cells and PARIS data from HeLa cells were used to determine how the structural model of MALAT1 changes in cancer." (PMID 33450947, 2021). "The survival analysis of MALAT1 expression in different cancer patients was evaluated by GEPIA database." (PMID 34308750, 2021). "There are several well-established lncRNAs that have been linked to cancers (e.g., HOTAIR, H19, MEG3, MALAT1)." (PMID 33803619, 2021). "As expected, all studies published so far on MALAT1 in cancer use primers that co-hybridize to genomic DNA." (PMID 34202021, 2021). "Our results showed that MALAT1 was differently expressed in different kinds of cancers using GEPIA, Oncomine, and TIMER databases to analyze." (PMID 34308750, 2021). "As reported in several studies, MALAT1 serves as a potentially valuable biomarker in cancer diagnosis and prognosis." (PMID 34821640, 2021). "The strong correlation between MALAT1 expression and cancer, as well as numerous known interactions with miRNAs and proteins that can bind to MALAT1, has made MALAT1 a promising biomarker and anticancer therapeutic target." (PMID 33450947, 2021). "The full extent to which the proposed structural alterations affect cancer cell development and progression await experimental validation, from establishing a secondary structural model of MALAT1 to confirming isolated structure-function relationships." (PMID 33450947, 2021). "The function and mechanism of Ψ on lncRNA and cancer progression remain to be elucidated, although many Ψ sites have been identified on different lncRNA transcripts, including MALAT1, SRA1 and XIST." (PMID 33564819, 2021). "This study revealed that MALAT1 was weakly expressed in the subcutaneous WAT in CAC patients and its association with a low index of fat mass and poor prognosis in cancer patients." (PMID 33691715, 2021). "MALAT1 has been demonstrated to be involved in many cancers, cardio-cerebrovascular disease, and hematological malignancies." (PMID 33726486, 2021). "MALAT1 expression was closely related to prognosis and tumor immune cell infiltrating among different cancer patients." (PMID 34308750, 2021). "MALAT1 has unique mechanisms of action in different types of cancer, which acts as an oncogenic lncRNA in HCC and is often highly expressed." (PMID 34821640, 2021). "For example, MALAT1 is over-expressed in several cancer types, and knockdown of MALAT1 reduces both the proliferation and metastasis of tumor cells in several mouse models." (PMID 34303380, 2021). "For example, the lncRNA MALAT1 can regulate multiple biological processes during the development of several cancers." (PMID 33927753, 2021). "Other evidence regarding the carcinogenic role of MALAT1 in various cancers have been reported by its functioning as a competitive endogenous (ce)RNA to propel the EMT and metastasis." (PMID 34638541, 2021). "As a long non-coding RNA, recent studies have revealed the role of MALAT1 in cancer metastasis and PTC malignant process via several mechanisms such as angiogenesis and gene expression regulation." (PMID 34805166, 2021). "MALAT1, for example, a lncRNA frequently upregulated in cancer, contains several m6A modifications that impact on its functional activity." (PMID 34530916, 2021). "Overexpression of lncRNA MALAT1 in diffuse large B cell lymphoma (DLBCL) causes effector T cell apoptosis and anergy, by upregulating PD-L1 expression on cancer cells." (PMID 34943820, 2021). "Research has shown that MALAT1 can be used as a biomarker for the diagnosis of many kinds of malignant tumors." (PMID 34778078, 2021). "As in the case of MALAT1, most of the published studies on the effects of m6A marks on the functions of lncRNAs are related to cancers." (PMID 34065036, 2021).
cancer (continued). "Metastasis-associated lung adenocarcinoma transcript 1 (MALAT1), also known as nuclear-enriched abundant transcript 2 (NEAT2), is another lncRNA significantly overexpressed in various cancers, and has been extensively studied in OC." (PMID 34680193, 2021). "In our study, we found that MALAT1 was weakly expressed in the subcutaneous WAT of CAC patients and was closely associated with low FMI and poor prognosis in cancer patients." (PMID 33691715, 2021). "Silencing of MALAT1 reduces the proliferation, invasion, and migration of cancer cells, and induces their apoptosis." (PMID 35145971, 2021). "In terms of cancer, MALAT1 was initially identified as an RNA whose expression is upregulated in primary lung tumors that had higher metastatic abilities." (PMID 34268119, 2021). "Although MALAT1 is abundant in normal cells, many studies have shown that this lncRNA promotes cell proliferation, migration, and metastasis in cancer tissues by affecting several signaling pathways, such as Wnt/β-catenin and PI3K/AKT." (PMID 34771549, 2021). "Metastasis-associated lung adenocarcinoma transcript-1 (MALAT1) is a evolutionarily conserved 7–9 kbp lncRNA, which is known to be associated with cancer development and metastasis." (PMID 34419065, 2021). "An immunological role of MALAT1 among different kinds of cancers was also determined in TIMER database." (PMID 34308750, 2021). "To date, MALAT1 overexpression has been shown in multiple human cancers, such as ovarian, bladder and colorectal cancers." (PMID 34527584, 2021). "That study postulated that, in cancer cells, the MALAT1 structure likely varies, thereby influencing cancer progression." (PMID 33450947, 2021). "In this study, we found that MALAT1 RNA level was related to 11 types of cancers, including BLCA, SKCM, PRAD, and so on." (PMID 34308750, 2021). "Many studies have demonstrated that the abnormal expression of MALAT1 is closely related to cancer pathophysiology, and has the potential to be translated clinically." (PMID 35127729, 2021). "Though most studies demonstrated a role for MALAT1 in various cancer types, MALAT1 overexpression was recently reported to prevent neuron apoptosis, promote neurite outgrowth, and reduce inflammation in two AD mouse models." (PMID 35052379, 2021). "Suppression of MALAT1 blocked the proliferation, invasion and migration ability of cancer cells and inhibited the expression of UBE2C." (PMID 34257576, 2021). "MALAT1 is a highly expressed lncRNA in many tissues and participates in a series of physiological and pathological processes, including myogenesis, cancer, aortic aneurysm, etc.." (PMID 33691715, 2021). "MALAT1 SNPs influenced the resistance of cancer cells to oxaliplatin through the regulation of their expression level." (PMID 34199840, 2021). "In conclusion, we analyzed the expression of MALAT1 and prognostic significance across different cancers from different public databases." (PMID 34308750, 2021). "MALAT1 is also upregulated in OC spheroids when compared to their adherent counterparts, suggesting a role of MALAT1 in cancer cell stemness." (PMID 34680193, 2021). "At the functional level, MALAT1 has been shown to bind various miRNAs, which promoted or decreased cancer progression." (PMID 33477898, 2021). "Since MALAT1 is ubiquitously expressed in almost all human tissues and upregulated in almost all types of cancer, further studies of MALAT1 in other cancers, such as HCC, will undoubtedly provide insight into its roles in tumorigenesis." (PMID 34001866, 2021). "Other cancer stem cell markers such as MALAT1 and NEAT1 were upregulated in PDS‐grown cells, while expression of ETV1 was downregulated in PDS‐grown cells compared to 2D‐grown cells." (PMID 33356003, 2021). "The upregulation of MALAT1 has been observed in different cancer types, including endometrial and cervical cancer, where there is an association with increased tumorigenesis and reduced survival." (PMID 34204445, 2021).
cancer (continued). "Upregulation of MALAT1 promotes cancer cell proliferation, and its downregulation promotes cancer cell death and autophagy." (PMID 35145971, 2021). "Recently, a growing number of reports suggested that MALAT1 acts as a ‘sponge’ to bind specific miRNAs and upregulate miRNAs’ targets to modulate cancer progression." (PMID 34268119, 2021). "Some cancer-related lncRNAs (e.g., MALAT1, HOTAIR, GAS5, and lincRNA-p21) were found to be enriched in exosomes, suggesting that lncRNAs disseminate cell signals and alter the local cellular microenvironment via EVs." (PMID 33514011, 2021). "HOTAIR and MALAT1 were the two lncRNAs of which the expression in liver metastases was always observed to be higher than the adjacent non-cancer tissues." (PMID 34307387, 2021). "It is possible that MALAT1 has different effects in different cancer types, but the true role of the transcript in cancer remains undecided." (PMID 34940760, 2021). "MALAT1 has a variety of oncogenic functions in many cancers including breast cancer to renal cell carcinoma and often correlates with decreased survival rates." (PMID 34440137, 2021). "In CC, the expression of MALAT1 is known to be significantly augmented in cancer cells and tissues, most probably by IL-6/STAT3 and HPV18 E6/E7 mediated signaling pathways." (PMID 34885213, 2021). "MALAT1, a long noncoding RNA commonly found to be hyperexpressed in cancer, is also essential for trophoblast invasion and proliferation in the early stages of pregnancy, and it was found to be downregulated in patients with PE." (PMID 34630130, 2021). "Its advantage lies in that it can reduce the harm of biopsy through noninvasive sampling and has important significance for the early diagnosis of cancer, but the low expression level of MALAT1 in blood makes sensitive analysis difficult." (PMID 34778078, 2021). "JMJD1A has been shown to upregulate Metastasis Associated Lung Adenocarcinoma Transcript 1 (MALAT1), a long non-coding RNA that is involved in dysregulation of cell signaling and EMT induction, cancer cell migration and invasion." (PMID 33803458, 2021). "In previous studies, MALAT1 was found to affect proliferation and metastasis in various cancers via MAPK signaling pathways." (PMID 34001866, 2021). "Multiple studies have demonstrated that the inhibition of MALAT1 impairs the proliferative and invasive properties of cancer cells, which further supports the involvement of MALAT1 in cellular transformation and/or tumorigenesis." (PMID 33691715, 2021). "The immunological characteristics of MALAT1 in different cancers were also determined in TIMER database." (PMID 34308750, 2021). "Metastasis-associated lung adenocarcinoma transcript 1 (MALAT1) plays an important role in the pathogenesis and development of various cancers." (PMID 34759954, 2021). "The long noncoding RNA MALAT1 is overexpressed in numerous cancers and plays a key role in cell proliferation and metastasis via the modulation of the PI3K/AKT, NF-kB, WNT/β-catenin, MAKP/ERK and other molecular signaling pathways." (PMID 34257576, 2021). "Moreover, IL-6 induced by MALAT1 could activate normal to cancer-associated fibroblast conversion." (PMID 33824303, 2021). "The upstream of MALAT1 contains 5 specific protein 1/3(SP1/3) binding sites, and the combined regulation of SP1 and SP3 in cancer cells promote the expression of MALAT1." (PMID 35145971, 2021). "LncRNA metastasis‐associated lung adenocarcinoma transcript 1 (MALAT1), also known as nuclear‐enriched abundant transcript 2 (NEAT2), is widely studied in several types of cancer." (PMID 34164906, 2021). "MALAT1 plays an important role in cancer and metastasis by regulation of gene expression or alternative splicing." (PMID 34906173, 2021). "NEAT1 plays an oncogenic role in most types of solid tumors, and MALAT1 which is related to cancer pathophysiology are both in Cluster93." (PMID 34906173, 2021).